NF1 (neurofibromin 1)
Diseases named in the same sentence as NF1 in open-access papers (continued):
Sharing a sentence is not in itself a finding about the gene and the disease.
astrocytomas (continued). "Additionally, we confirmed the presence of the NF1 p.Met992del pathogenic variant with LOH in three astrocytomas from a single case (UAB-R5571-F), confirming these as NF1-associated tumors." (PMID 30190611, 2019). "We analyzed the frequency of rs2151280 alleles/genotypes in our cohort by comparing them with those of the healthy population, also considering the allele or genotype distribution within NF1 patient subgroups showing DNFs, PNFs, OPGs, or other tumors (e.g., astrocytomas and MPNSTs)." (PMID 31694342, 2019). "Both patients disclosed a severe clinical picture, which in the case of NF_8 the spinal form of NF1 was associated to learning disabilities and obesity, while in NF_72 the disease phenotype was complicated by 25-OH vitamin D deficiency as well as optic glioma and astrocytoma." (PMID 35885913, 2022). "The NFIA gene encodes a member of the nuclear factor 1 (NF1) family of transcription factors, and has been associated with cancer prognosis in some cancers, such as astrocytomas, and may be associated positively or negatively with prognosis depending on the tumor type." (PMID 33092094, 2020). "Cases with a history of NF-1, germline NF1 mutation, or methylation class match to high-grade astrocytoma with piloid features (HGAP) were excluded." (PMID 40985888, 2025). "Here, we briefly highlight large-scale drug screening strategies aimed at identifying therapeutic targets for astrocytomas and GBMs in NF1." (PMID 41294711, 2025). "This association is illustrated by two patients: patient (P20) with NF1 had an astrocytoma in the brain stem, and patient P25 with NF2 had a meningioma and bilateral acoustic neuromas." (PMID 34325699, 2021). "A histologically distinctive subtype of astrocytoma was recently described in individuals with NF1, which is similar to subependymal giant cell astrocytoma frequently observed in individuals with tuberous sclerosis complex (“SEGA-like astrocytomas”)." (PMID 31906320, 2020). "Molecular analysis revealed the NF1 pathogenic variant c.2970_2972del with LOH at c.2970_2972del and all three intragenic NF1 microsatellite markers tested in all three astrocytomas, confirming these as NF1-associated tumors." (PMID 30190611, 2019). "This is in agreement with the findings of the Parada14 and Gutmann39 labs in the context of pNF and astrocytoma (low-grade optic glioma), respectively, in which they concluded that an Nf1+/− microenvironment is critical for these tumors’ formation." (PMID 30479396, 2018). "Both compounds appeared to selectively inhibit proliferation in mouse Nf1-deficient astrocytoma cell lines without affecting normal primary astrocytes or astrocytes with heterozygous Nf1 loss." (PMID 41294711, 2025).
astrocytomas (continued). "In NF1-associated tumors, particularly astrocytomas, ATRX mutations and ALT are associated with specific tumor groups such as the recently recognized WHO tumor type high-grade astrocytoma with piloid features." (PMID 35740680, 2022). "This might be related to the fact that almost all NF1-related OPGs are pilocytic grade 1 astrocytomas and tend to grow more slowly compared to sporadic cases." (PMID 35328218, 2022). "Although experimental data shows that loss of NF1 in mice results in increased cell proliferation, loss of NF1 does not necessarily result in the formation of astrocytomas." (PMID 33237934, 2020). "However, we have previously demonstrated that functional loss of ATRX and activation of ALT are frequent features of diffuse and high-grade astrocytomas that develop in patients with NF1, and are present in 7 (58%) and 8 (67%) respectively." (PMID 31462295, 2019). "Importantly, somatic single nucleotide variants, including the IDH1R32H mutation, which typifies low-grade astrocytoma, as well as pathogenic NF1 variants, are detected in the non-diseased human brain." (PMID 38308315, 2024). "Furthermore, sequencing of three subependymal giant cell astrocytoma (SEGA)-like astrocytomas in NF1 mutant patients with ALT and intact ATRX have revealed genetic alterations in RECQL4, Fanconi anemia complementation group genes (FANCD2, FANCF, and FANCG), and SMARCAL1." (PMID 34069193, 2021). "This cohort comprised 53 IDH1/2-mutant astrocytomas, 19 histone-mutant tumors, 7 with MAPK pathway alterations (BRAF, NF1), 19 GBM (13 pTERTmt) and 2 OD (1pTERTmt)." (PMID 41422096, 2025). "Moreover, the deactivation of the neurofibromin 1 (NF1) gene has been associated with heightened proliferation of glial progenitor cells and the emergence of optic gliomas, providing insights into the genetic pathways that underlie the development of astrocytomas." (PMID 38807869, 2024). "mTOR activation has also been associated with a particular subset of pilocytic astrocytomas called the “low-grade astrocytoma subtype intermediate” (LGSI), found in patients with syndrome neurofibromatosis 1 (NF-1)." (PMID 23717811, 2013). "Generation of Nf1 knockout mice from the germline (Nf1−/−) was unsuccessful as they were lethal and their heterozygous littermates (Nf1+/−) did not develop astrocytomas despite increased astrocyte proliferation." (PMID 38804352, 2024).
astrocytomas (continued). "Like NF1 patients, NPcis mice spontaneously develop predominantly soft tissue sarcomas including MPNSTs (genetically engineered murine (GEM) PNSTs) and malignant Triton tumors, as well as rhabdomyosarcomas and astrocytomas that severely limit their life expectancy to ~5 months." (PMID 32650362, 2020). "Although the patient did not harbor any signs or family history of NF1, to exclude a SEGA‐like astrocytoma, we performed DNA methylation profiling, which definitely classified this case as SEGA." (PMID 39492623, 2025).
Cognitive impairment (67 papers, 2003 to 2026). Abnormal cognition is characterized by deficits in thinking, reasoning, or remembering. "Because of the consequent reduction in cAMP levels, aberrant dopaminergic signaling has also been implicated in attention and cognitive deficits in mouse NF1 models." (PMID 38667335, 2024). "Neurofibromatosis 1 (NF1) is a single-gene disorder associated with cognitive impairments, particularly with deficits in working memory." (PMID 35673329, 2022). "NF1-deleted patients were previously reported to develop a particularly severe form of the disease with frequent cognitive impairment and an increased risk of benign and malignant tumors." (PMID 34199217, 2021). "T2 hyperintensities were also noted in NF1+/ex42del minipigs, which have been associated with cognitive impairment in individuals with NF1." (PMID 33669386, 2021). "Patients with NF1 who have mutations in the LRD coding region were described to be more prone to developing cognitive deficits than those with mutations elsewhere in the NF1 gene." (PMID 32858845, 2020). "When NF1 is mutated, this pathway is affected, possibly influencing neuronal development and cognitive deficits associated with the disease." (PMID 32858845, 2020). "Future studies will also evaluate NF1-associated cognitive deficits and neuro-developmental disabilities in our minipigs." (PMID 30302402, 2018). "Despite being caused by mutations in a single gene, NF1, the expressivity of the disease ranges from mild cutaneous manifestations to severe, life-threatening complications, including malignant tumors, skeletal deformities, and cognitive impairments." (PMID 41987183, 2026). "Finally, p.Lys1423 missense variants were associated with more severe NF1, with more frequent plexiform and spinal NFs, bone abnormalities, Noonan-like features, cardiovascular abnormalities and cognitive impairment or learning difficulties." (PMID 40759488, 2025). "Therefore, all methods and attributes of the system can be utilized to explore various aspects of behavioral pathology and cognitive deficits pertinent to NF1, to facilitate elucidation of molecular mechanisms underlying them." (PMID 38667335, 2024). "The genetic facility and versatility of Drosophila may provide answers to this question, as elucidating the mechanisms of synaptic dysfunction in NF1 holds promise towards therapeutic strategies for the associated cognitive impairments." (PMID 38667335, 2024). "Although lipophilic statins are thought to readily cross the blood-brain barrier, it might be that other RAS-RAF-MEK-ERK signaling inhibitors are better suited to treat NF1-associated cognitive deficits in human patients." (PMID 36037004, 2022). "Considering that hippocampus-dependent memories are regulated by MAPK activity oscillation, our data suggest that the circadian oscillation of MAPK activity may be one of reasons which cause the cognitive defects in Nf1+/− mice." (PMID 28673309, 2017). "Work in animal and cellular models have also shown that disruption of the Ras signalling cascade has downstream effects on dopaminergic function that may partially explain the cognitive deficits associated with NF1." (PMID 28694877, 2017). "It should be emphasized that this transient MEKi treatment protocol also rescued structural defects in the other regions of the Nf1hGFAPCKO brain including the enlarged corpus callosum, a brain structural defect associated with severe cognitive impairments in a subset of NF1 patients." (PMID 25535838, 2014). "Drosophila models deficient for neurofibromin have also been used to determine if the learning deficits seen within mammalian samples are caused by the developmental abnormalities seen in NF1 or if the cognitive defects are due directly to decreased neurofibromin activity." (PMID 16524466, 2006).
Cognitive impairment (continued). "Pre-existing clinical conditions associated with cognitive impairment must also be taken into consideration including developmental delay and autism spectrum disorder, but particularly those associated with brain tumour development, such as NF-1 and tuberous sclerosis." (PMID 40149283, 2025). "Interestingly, our results demonstrated a higher frequency of cognitive disorder, including delayed acquisition of psychomotor skills and residual multi-domain cognitive impairment, in patients carrying NF1 frameshift mutations (OR 6.2, CIs 1.626 to 23.64, p < 0.01)." (PMID 35885913, 2022). "Furthermore, based on the conserved expression pattern of NF1 in human brain, it is suggested that the enriched expression of NF1 in inhibitory neurons may underlie cell type-specific pathophysiology and cognitive deficits in NF1." (PMID 31752929, 2019). "The present findings provide a first evidence for a role of circuits controlling NF1 transcript processing in modulating phenotypic expressivity in NF1, and document an association between the levels of neurofibromin isoform I mRNA and the severity of phenotype and cognitive impairment." (PMID 31730495, 2019). "The present findings provide preliminary evidence for a role of circuits controlling NF1 transcript processing in modulating NF1 expressivity, and document an association between the levels of neurofibromin isoform I mRNA and the severity of phenotype and cognitive impairment in NF1." (PMID 31730495, 2019). "Patients with NF1 microdeletions have been reported to exhibit a more severe clinical phenotype than patients with intragenic NF1 mutations, as evidenced by an increased risk of MPNSTs, severe learning disability, cognitive impairment, developmental delay and dysmorphic facial features." (PMID 23101500, 2012). "The observed sizes of group differences are likely smaller than the group differences observed for other more established phenotypes of NF1 including cognitive deficits, ASD, and ADHD." (PMID 39844170, 2025). "The cancer-related morbidity, and developmental and cognitive disorders are major contributors to the lower educational attainment of individuals with NF1." (PMID 37460655, 2024). "Comprehensive searches of databases including PubMed, Embase, and the Cochrane Library were performed up to March 31, 2023 to identify randomized controlled trials (RCTs) investigating the effects of statins on cognitive impairments in children with NF-1." (PMID 37876519, 2023). "Despite these limitations, the existing evidence still unveils that statins are ineffective in improving cognitive impairments in pediatric patients with NF-1." (PMID 37876519, 2023). "Behavioral alterations and cognitive deficits have been found in 50–70% of children with Nf1 and include specific problems with attention, visual perception, language, learning, attention, and executive function." (PMID 37760547, 2023). "The cognitive impairments observed in heterozygous Nf1 mice have also been rescued by inhibition of the Ras-MAP kinase cascade." (PMID 37760547, 2023). "Accordingly, both human and mouse studies demonstrated that NF1 males showed more propensity to cognitive impairments." (PMID 37101298, 2023). "A significantly higher proportion of scNFs, pNFs, skeletal abnormalities, dysmorphism, cognitive impairment, learning disabilities, and cardiovascular abnormalities were observed in type-1 deleted patients when compared to the “classic” NF1 group." (PMID 34199217, 2021). "Together with the present results, these findings suggest that both enhanced Erk and mTOR activities contribute to cognitive impairment in NF1 and that deregulation of each pathway affects distinct cognitive functions." (PMID 34576341, 2021). "Our study indicates a prevalence of global developmental delay, cognitive deficits, attention deficit and autistic symptomatology in children with NF1 microdeletions which is significantly higher than that observed in the general NF1 population." (PMID 32533297, 2020).
Cognitive impairment (continued). "NF1 is a rare monogenetic, autosomal dominant genetic disorder caused by mutations in the tumor suppressor gene neurofibromin 1 (17q11.2, MIM*613113) in which a broad spectrum of cognitive deficits occur in 30–70% of cases." (PMID 28262833, 2017). "In the 3 years following this presentation, multiple NF1 features appeared, including macrocephaly, Lisch nodules, multiple café au lait patches, cerebral gliomas, and cognitive impairment." (PMID 26514695, 2015). "Given the familial link, and the newly emerged macrocephaly, Lisch nodules, multiple café au lait patches, cerebral gliomas and cognitive impairment, a diagnosis of NF1 was made." (PMID 26514695, 2015). "More than 50% of individuals with mutations in NF1 also have cognitive impairments and recent studies report a significant increase in the incidence of ASD in NF1 patients." (PMID 26483618, 2015). "It is proposed that the cognitive deficits in NF1 are the result of dysfunctional cellular trafficking and localization of molecules downstream of the primary gene defect." (PMID 16524466, 2006). "Studies of specific learning disability in children with NF1 show intellectual impairment in as many as 40% of the children in some series." (PMID 14647135, 2003). "While Neurofibromatosis Type 1 (NF-1) patients are predisposed to developing brain tumours, it is also associated with cognitive impairment without any brain tumours." (PMID 40149283, 2025). "For example, although mouse models of Nf1 develop most hallmark developmental and cognitive deficits, they do not present with apparent freckling or CALs." (PMID 38667335, 2024). "Intriguingly, statins have also been confirmed to alleviate cognitive impairments in NF1 mice." (PMID 37876519, 2023). "Overall, results suggest that NF1 is characterised by aberrant resting state oscillatory activity that may contribute towards the cognitive impairments experienced in this population." (PMID 37608248, 2023). "Firstly, cognitive deficits and behavioral irregularities in NF-1 patients may stem from diverse pathways." (PMID 37876519, 2023). "Behavioral alterations and cognitive deficits have been found in 50–70% of children with Nf1." (PMID 37760547, 2023). "When present, NF-1-associated CVD clinical manifestations may include headache, cognitive deficits and ultimately aneurysm rupture, causing death." (PMID 33395412, 2021). "Indeed, clinical trials using simvastatin for the treatment of NF1 have shown little promise, while trials with lovastatin show an improvement in cognitive deficits." (PMID 31147392, 2019). "Along with structural abnormalities in CNS, several lines of evidence suggest that the distribution of NF1 in single neuronal cell type may also contribute to cognitive deficits in NF1." (PMID 31752929, 2019). "There is no controlled data as yet to confirm a specific link between peripheral pMAPK assay and neural Ras function in human NF1 (although links have been found in cognitive impairment and Alzheimer’s disease); further work will be necessary to confirm its value as a biomarker." (PMID 29484149, 2018). "Furthermore, previous studies have demonstrated elevated p-MAPK activity in animal models of NF1 result in cognitive deficits, the Western blotting data verified this result." (PMID 28673309, 2017). "Conversely, work with NF1 mutant mice showed an increased GABA release as well as GABAergic transmission, and hypothesized them to be a cause for cognitive impairment." (PMID 24904277, 2014). "Among the most frequent clinical features observed in patients with type-1 NF1 deletions were dysmorphic facial features, macrocephaly, hyperflexibility of the joints, large hands and feet, cognitive impairment/learning disability, and a high tumor load as well as an increased risk of MPNSTs." (PMID 22151963, 2011).